CXCR1 (C-X-C motif chemokine receptor 1)
Diseases named in the same sentence as CXCR1 in open-access papers (continued):
Sharing a sentence is not in itself a finding about the gene and the disease.
tumor (continued). "Using BMT, we show that CXCR1‐mediated tumor cell–endothelial interactions are not sufficient for NRAS‐driven lung metastasis, which also requires the concurrent involvement of myeloid cells that express CXCR2." (PMID 28341702, 2017). "Importantly, studies have demonstrated critical role of CXCR1 and CXCR2 in tumor growth and metastasis and serves as the key target for the development of novel therapies." (PMID 28484461, 2017). "The enrichment analysis also demonstrates activation of the IL-8/CXCR1/CXCR2 pathway in the BM cells that are crucial for the activation of multiple intracellular signaling pathways to regulate proliferation, differentiation, and migration of tumor cells." (PMID 28626727, 2017). "It is tempting to speculate that an autoregulatory feedback loop may be in place in which TME-derived IL-8 initially induces tumor cell EMT and brachyury expression, which in turn upregulates MUC1-C, the NF-κB pathway, and finally IL-8 and CXCR1 expression." (PMID 27348007, 2016). "Consistent with the tumour growth data, in obese, but not in lean, mice there was a sevenfold higher frequency of CXCR1+ ASCs observed in CXCL1-sh-RM1 tumours, compared with control-sh-RM1 tumours." (PMID 27241286, 2016). "Up-regulation of CXCR1 in Notch+ derived spheres is also correlated with higher stem-like potential, as it has been shown to be almost exclusively expressed in the CSC population as compared to bulk tumor cells." (PMID 27292795, 2016). "In addition, small molecule antagonists of CXCR1 and CXCR2 inhibited liver metastasis of CRC by decreasing tumor angiogenesis and inducing tumor cell apoptosis in a mouse model." (PMID 27136535, 2016). "CXCR1 is a receptor for the cytokine IL-8, and it has been showed that recombinant IL-8 increased BCSC self-renewal as determined by the ability of these cells to form tumor spheres as well as by increased ALDH expression." (PMID 26517518, 2015). "In contrast, inflammatory cells in the area surrounding the tumor were negative for IL-8, while lymphocytes in these areas were weakly positive for IL-8R/CXCR1." (PMID 25123545, 2014). "Thus, the blockade of CXCL8 receptors CXCR1 and CXCR2 arises as a promising side-therapy attempting to avoid tumor recurrence." (PMID 25165728, 2014). "The tumor cells were positive for G-CSF, partly positive for IL-8 and weakly positive for IL-6, but negative for IL-8R/CXCR1." (PMID 25123545, 2014). "MSCs may be recruited into the tumor through FPR2, CCR2, CXCR1, CXCR2, CXCR4, CXCR6, and CX3CR1 depending on the types and locations." (PMID 25110692, 2014). "Although CXCL8 or CXCR1/2 siRNAs have not yet been used clinically, a pre-clinical orthotopic ovarian cancer model has illustrated anti-tumor effects upon silencing of CXCL8 gene expression using liposome-encapsulated siRNA." (PMID 24276377, 2013). "In addition, IL8 functions as a stem cell regulator as shown by up-regulation of IL8 receptor, CXCR1, in breast CSCs and increased breast CSC self-renewal and tumor growth by exogenous IL8." (PMID 23799116, 2013). "CXCR1 and CXCR2 which are encoded by two distinct genes are expressed in most cancer cells with no apparent correlation with the grade of the tumor." (PMID 22235381, 2011). "Whatwe document is that IL-8 mediates the retention inside the tumor microenvironment.This is not a surprise since IL-8 receptors, CXCR1 and CXCR2, are expressed on DCand are functional in classical chemotaxis assays." (PMID 21423807, 2011). "Interestingly, CXCR1 or CXCR2 overexpression in SBC-2 cells induced tumourigenicity, and A375P cells significantly enhanced tumour growth as examined in vivo." (PMID 19401689, 2009). "Likewise, interferon response genes (including TLR3, MX1, RSAD2, IFI44, IFI27, IFIT1, and IFIT3), and chemokine genes (including CCL7, CXCL10, CXCR1, and CCL25) were significantly increased in PM-treated MM tumor tissues, whereas panobinostat showed minimal effects at equivalent doses." (PMID 40562746, 2025).
tumor (continued). "Furthermore, there is a potential benefit in the combined blockade of CXCR1/2 and TGF-β signaling, which may modulate tumor plasticity and enhance tumor response to the PD-L1 blockade." (PMID 40006729, 2025). "Finally, the use of UM-SCC-11B and UM-SCC-74B cells transfected with siRNA targeting CXCR1 and CXCR2 further confirmed that removal of CXCR1/2 receptor signaling could sensitize HPV-negative HNSCC tumor cells to the cytotoxic activity of docetaxel in vitro." (PMID 39639338, 2024). "Specifically, tumor cells could produce chemokines, which activated CXCR1 and CXCR2 receptors on the surface of neutrophils to result in the formation of NETs, which surround tumor cells and protect them from direct contact with cytotoxic CD8+ T cells and NK cells." (PMID 38534538, 2024). "For instance, studies have shown that inhibition of IL-8/CXCR1/2 can reduce the recruitment of immune cells and decrease the levels of pro-inflammatory cytokines, thereby potentially mitigating the inflammatory environment within the TME and reducing tumour progression and treatment resistance." (PMID 39199570, 2024). "Genetic manipulation of CAR NK cells to express chemokine receptor CXCR1, which binds to the proinflammatory chemokine IL‐8 secreted by cancer cells and stroma cells in TME, enhanced CAR NK infiltration into tumor sites, reduced tumor burden and prolonged survival of tumor xenografted mice." (PMID 38045827, 2023). "Activation of chemokine receptors (CXCR1 and CXCR2) has pro-angiogenic and pro-inflammatory effects, inducing several signaling pathways, such as the protein kinase C, phospholipase C, PI3K/AKT/mTOR, RAS/RAF/MEK/ERK and NF-kB pathways, promoting tumor cell survival, proliferation, and dissemination." (PMID 37190141, 2023). "In addition, CXCL8 may directly stimulate CXCR1- or CXCR2-expressing tumor (microenvironmental) cells, stimulating their survival, proliferation, and migration further enhancing tumor expansion." (PMID 36725964, 2023). "Results showed tumor cells usually have negative CXCR1 and CXCR2 staining." (PMID 37765018, 2023). "As a matter of fact, blocking CXCR1 or CXCR2 in neutrophils upon coincubation with supernatant from various chemokine-producing carcinoma cell lines abrogated NET formation, which argues for the involvement of CXCR1 and CXCR2 ligands in tumor-mediated NET formation." (PMID 35979369, 2022). "The ELR+CXCL/CXCR1/2 axis has never been studied in MB, which are highly vascularised tumours." (PMID 36497191, 2022). "These inflammatory CAFs released factors that enhanced tumor cell dispersion, scattering, and migration; the inflammatory CAF-derived factors elevated cancer cell migration by stimulating the chemokine receptors CCR2, CCR5, and CXCR1/2 and Ras-activating receptors, expressed by the cancer cells." (PMID 33806906, 2021). "Administration of a dual CXCR1/2-targeted antagonistic peptide alone inhibited the growth of PTEN-deficient but not PTEN-expressing DU145 and PC3 xenograft tumours, consistent with our prior and current demonstration of CXCL8 functioning as a key survival factor in this genetic context." (PMID 32743555, 2020). "Of note, an increased expression of IL-17 (IL-17RA), IL-8 (CXCR1) and CCL2 (CCR2) receptors was also observed on M-DM exposed to CM from bcl-2 overexpressing clone, suggesting a larger impact of cancer cell-specific bcl-2 on the interplay between the tumor and the stromal compartment." (PMID 32269145, 2020). "Interestingly, the CXCR1/2-targeted pepducin was equi-effective in enabling an antitumour response as a clinically relevant dose of radiation in both PTEN-depleted DU145 and PC3 tumours." (PMID 32743555, 2020). "IL‐8/CXCR1 cells were confined within certain areas of the tumor, but did not cluster together." (PMID 30883740, 2019).
tumor (continued). "Furthermore, tumor exoRNAs can activate lung epithelial cell TLR3 to recruit neutrophils due to the expression of chemokine receptors (CXCR1, CXCR2, CXCR4, andCCR2) being higher in tumor-bearing Tlr3−/− mice, consequently inducing lung premetastatic niche formation." (PMID 30849983, 2019). "Within the tumour microenvironment, IL‐8 signalling is initiated by binding of its G‐protein‐coupled receptors CXCR1/2.33, 39 To examine whether ZNF143 expression affects on IL‐8 signalling in cancer cells, we examined the mRNA expression of CXCR1/2." (PMID 30933430, 2019). "In addition, CCR6/CCL20 interaction in endometrial adenocarcinoma, CXCR1/2/CXCL7 interaction in clear cell renal cell carcinoma, CXCR2/CXCL8 interaction in nasopharyngeal carcinoma, and CXCR6/CXCR16 interaction in HCC are reported to promote tumor cell growth." (PMID 25110692, 2014). "RT-PCR showed that CXCR1 mRNA was strongly expressed in the non-cancerous area around the tumor." (PMID 25123545, 2014). "Notably, exogenous human IL-8 did not activate the CXCR1 pathway and could not facilitate tumour escape from PBMC therapy." (PMID 41163221, 2025). "The increased exposure of neoantigens and expression of chemokines in tumor cells induced by radiotherapy may offer new avenues for CAR-NK therapy development, such as CARs targeting NKG2DL or overexpressing chemokine receptors (CXCR1, CXCR2, and CXCR4) through CAR design." (PMID 38162672, 2023). "Moreover, CXCR1 and CXCR2 are differentially expressed in human tissues, though in mouse, CXCR2 is the predominant receptor mediating response to the murine chemokine ligands during inflammation, angiogenesis, and tumor growth (CXCL1,2,3 and 5, also known as KC, MIP2α, MIP2β, and LIX)." (PMID 37270599, 2023). "As the binding receptors CXCR1 and CXCR2 are expressed on myeloid derived cells and carcinoma cells, CXCL1 expression in CAFs may serve to regulate paracrine signaling interactions with immune cells and cancer cells to promote chemo-resistance and tumor progression." (PMID 25344051, 2014). "Another compound being tested is ladarixin/DF2156A, a non-competitive allosteric inhibitor of CXCR1 and CXCR2 receptors, which has demonstrated anti-tumor properties for melanoma and PDAC." (PMID 40427171, 2025). "We evaluated cytokine production, NET formation and tumour response to GEM, with or without the CXCR1/2 inhibitor navarixin." (PMID 40993312, 2025). "It has been reported that depression promotes tumor growth and metastasis by affecting TAM/CXCL1 in the tumor microenvironment, but the downstream receptors of CXCL1 (such as CXCR1/CXCR2) have not been investigated in these studies." (PMID 40839237, 2025). "CXCR1 expression, not CXCR2, was shown to upregulate the tumor suppressor ITM2A to diminish cell proliferation and inhibit tumor growth." (PMID 39766038, 2024). "This is consistent with current scientific knowledge, as NK cells have low expression of CXCR1 and CXCR2 and are, therefore, not recruited to the tumor microenvironment by CXCR2 ligands." (PMID 37686093, 2023). "Raychaudhuri and Vogelbaum discovered that in GBM, the tumor cells do not express CXCR2; they only express CXCR1 while also expressing CXCL8." (PMID 36831112, 2023). "T-cells do not express the IL-8-responsive chemokine receptors, CXCR1 or CXCR2, and consequently they are unable to respond naturally to a tumor-derived gradient of IL-8." (PMID 31091832, 2019). "The majority of tumor-infiltrating mast cells expressed CXCR4 but not CCR2, CCR4, CCR5, CCR7, CXCR1, CXCR2 or CXCR7, while, mast cells in peritumoral or non-tumor tissues showed lower CXCR4 expression." (PMID 30808413, 2019). "CXCR1 was expressed equally in all carcinomas, as opposed to CXCR2 and 4, which were only expressed in few tumours." (PMID 29976164, 2018). "Both CXCR1 and CXCR2 were required for both spontaneous and induced lung colonization by these cells, but not for s.c. tumor growth (and EV2J and K)." (PMID 28341702, 2017).
tumor (continued). "Expression of CXCL1, CXCR1 and CXCR2 was elevated in tumour epithelium relative to normal adjacent tissue (P<0.001)." (PMID 21285972, 2011). "Comparison of the mean IRS scores for CXCR1, CXCR2 and CXCL1 in malignant and non-malignant tissue confirmed higher expression of each chemokine marker in the tumour epithelium relative to adjacent normal colorectal tissue." (PMID 21285972, 2011). "It is of great interest that the overexpression of CXCR1 or CXCR2 in SBC-2, a non-tumourigenic cell line induced tumour formation." (PMID 19401689, 2009). "Patients #5, #6, and #7 (without tumor samples) showed an overlap of four genes (SORL1, PTPRC, MIR6819, and NAMPT), while #6 and #7 also shared five genes (CELF2, EDEM3, SMCHD1, RAVER1, and CXCR1)." (PMID 39001407, 2024). "CXCR1 and CXCR2 are expressed in a variety of immune and non-immune cells, including tumor cells." (PMID 35837284, 2022). "These contrasting results could be explained by at least two mechanisms: first, inhibitors target both CXCR1 and CXCR2, and the differential role of these receptors in tumor biology has not yet been demonstrated." (PMID 35158948, 2022). "However, treatment with IR induced the expression of chemokine receptors CXCR1 and CXCR2 in tumour cells independent of PTEN status." (PMID 32743555, 2020). "Using these models, we found that co-expression of CXCR1 and CXCR2 with an αvβ6-specific CAR resulted in a significant increase in T-cell migration towards recombinant or tumor-derived IL-8, without alteration of CAR-mediated cytolytic activity or cytokine release." (PMID 31091832, 2019). "Furthermore, the IL-8/CXCR1/CXCR2 signaling was crucial for the maintenance of stemness features and tumor-initiating ability of TC cells, whereas CXCL1/CXCR2 was not." (PMID 28415590, 2017). "Since ASPC-1 and BxPC-3 cells do not express CXCR1 and CXCR2, our data favors a paracrine role for IL-8 in PDAC possibly through the stimulation of endothelial cell proliferation and/or mobilization to remodel tumor vasculature." (PMID 22815748, 2012). "The increased Treg infiltration of the tumor was independent of TGFβ signaling, suggesting a systemic distribution of CXCL8 and IL6 produced by cancer cells, which results in increased neutrophil production, Foxp3 upregulation on T lymphocytes, and tumor trafficking through CXCR1." (PMID 39409924, 2024). "Similarly the ectopic expression of CXCR1, which is not normally expressed on T cells, or CXCR2, on anti-CD70 CAR T cells, enhanced the trafficking to tumours and elicited tumour regression and improved survival in models of glioblastoma, pancreatic cancer, and ovarian cancer." (PMID 35205725, 2022).
cancer (241 papers, 2012 to 2026). A tumor composed of atypical neoplastic, often pleomorphic cells that invade other tissues. "CXCR1‐associated cancer cells express invasive attributes and metastasise faster, making the cells resistant to treatment." (PMID 38426619, 2024). "Here, compared to CXCR1 rs2234671 genotype, the C allele of CXCR1 rs2234671 has longer disease-free (p = 0.015), cancer-specific (p = 0.007) and overall survival (p = 0.002)." (PMID 36497451, 2022). "Differential expression of CXCR1 is associated with a variety of human pathologies including cancer and inflammatory diseases." (PMID 33226189, 2021). "Our findings further support the hypothesis that there is an association between CXCR1/2 expression and cancer cell invasion and metastasis in certain cancer types." (PMID 23420470, 2013). "Interestingly, PTPN11 and a receptor for IL8, CXCR1, have also been implicated in cancer stem cell self-renewal in the breast." (PMID 23113900, 2012). "The recruitment of neutrophils towards transformed or cancer cells depends on interleukin‐8 (IL‐8), which attracts CXCR1/CXCR2‐expressing neutrophils to sites of tissue damage and cancer." (PMID 41503514, 2026). "CXCR1/2 antagonists, aimed at disrupting IL-8-mediated neutrophil recruitment and cancer stem-like cell expansion, are in early-phase trials for metastatic breast cancer." (PMID 41007766, 2025). "Several CXCR1/2 small-molecule inhibitors have shown efficacy in preclinical models of inflammatory diseases and in combination treatments for cancer." (PMID 40427538, 2025). "A variety of CXCR1/2 inhibitors have been developed for the treatment of inflammation-related diseases, metabolic disorders, as well as various cancers." (PMID 39897048, 2025). "CXCR1/2, a G-protein coupled rhodopsin-like seven transmembrane domain receptors, is mainly expressed on neutrophils, macrophages, as well as cancer cells, and is indispensable for CXCL8-mediated signaling activation and biological function." (PMID 39897048, 2025). "IL-8 attracts immune cells like neutrophils that, instead of fighting the cancer, create an environment through its receptor CXCR1/CXCR2 signaling that helps tumors survive, invade new areas, and avoid immune attack." (PMID 41002568, 2025). "Conversely, ABCB5 demonstrates a strong association with chemoresistance and immune suppression, driven by its role in regulating cancer stemness and IL-1β/IL-8/CXCR1 signaling loops." (PMID 40445912, 2025). "Neutrophils and MDSCs are two major myeloid-derived cells that foster the interaction between cancer cells and the IL-8/CXCR1/2 axis." (PMID 39199570, 2024). "Given that anti‐CXCL8 and anti‐CXCR1/2 drugs are in advanced stages of clinical development for the treatment of cancers and other diseases, combinatorial therapies involving these drugs and clinically available anti‐EGFR drugs are a real possibility." (PMID 38757578, 2024). "By interfering with CXCL8, CXCR1/2 activates variable signaling pathways in cancer cells, including the RAS–RAF–MEK–ERK and PI3K–AKT–mTOR pathways." (PMID 38756650, 2024). "Overexpression of all genes was found in stage 3 cancer patients compared to that in normal tissues, except CXCR1 which was upregulated in patients with stage 4 disease." (PMID 38426619, 2024). "An in vitro study showed that IL-8 interaction with C-X-C motif chemokine receptor 1(CXCR1) complements Capan1 sphere-forming properties and contributes to cancer progression by increasing the proportion of cancer stem cells." (PMID 39457656, 2024). "The pivotal role of IL-8 expression in FME contributes to the enrichment of CSC properties via paracrine signaling IL-8 subsequently triggers cancer cells to generate IL-8 in an autocrine manner via CXCR1, resulting in cancer progression." (PMID 38891100, 2024). "Inflammatory cytokines that activate CXCR1 can activate downstream signalling pathways that improve cancer cell survival and increase resistance to certain treatments." (PMID 38426619, 2024).